BIN1 (bridging integrator 1)
Diseases named in the same sentence as BIN1 in open-access papers (continued):
Sharing a sentence is not in itself a finding about the gene and the disease.
centronuclear myopathy (continued). "The histopathology and the cellular organization defects of the human and canine muscle disorders are almost identical, we therefore consider IMGD as a faithful mammalian model for BIN1-related centronuclear myopathy." (PMID 23754947, 2013). "The ubiquitously expressed BIN1, altered in centronuclear myopathy (CNM) and myotonic dystrophy (DM), possesses a muscle-specific exon coding for a phosphoinositide binding domain." (PMID 23754947, 2013). "Mutations in myotubularin, amphiphysin 2 (BIN1), and dynamin 2 lead to different forms of centronuclear myopathy, while mutations in myotubularin-related proteins cause Charcot-Marie-Tooth neuropathies." (PMID 22496665, 2012). "In conclusion, this study expands the phenotypic spectrum of BIN1-related centronuclear myopathy and is the first clinical description of intrafamilial variability in a consanguineous CNM family." (PMID 21129173, 2010). "In addition to the BIN1-related form, heterozygous missense variants in hJUMPY, a novel phosphoinositide phosphatase with functional similarities to myotubularin, were recently identified in two sporadic cases with features of centronuclear myopathy and an additional DNM2 mutation in one case." (PMID 18817572, 2008). "Centronuclear and myotubular myopathies (CNMs) are rare, inherited muscle disorders characterized by muscle atrophy, weakness, and altered muscle fiber structure, primarily caused by mutations in MTM1, DNM2, or BIN1." (PMID 41373724, 2025). "The concurrent role of Bin1 and DNM2 in TT biogenesis has been confirmed by studies performed in Bin1 knockout mice and by the identification of mutations in both genes that are causative of human centronuclear myopathy." (PMID 35454077, 2022). "X-linked CNM (XLCNM, also called myotubular myopathy) is caused by mutations in the phosphoinositide phosphatase myotubularin (MTM1; MIM#310400) and autosomal dominant and recessive CNM due to mutations in the DNM2 partner amphiphysin 2 (BIN1; MIM#255200)." (PMID 36369230, 2022). "BIN1 and DNM2, which encode a BAR domain protein BIN1 and dynamin 2, respectively, have been reported to be causative genes of centronuclear myopathy (CNM), a hereditary degenerative disease of skeletal muscle, and deformation of T-tubules is often observed in the CNM patients." (PMID 33187981, 2021). "Moreover, the localization of N-WASP is also altered in the muscle of a CNM2 patient with a BIN1 mutation outside the SH3 domain (R154Q), showing that mis-regulation of N-WASP by BIN1 is key in centronuclear myopathy pathophysiology." (PMID 32164332, 2020). "Similarly, the identification of DNM2 and BIN1 as genetic modulators of MTM1, all of which cause a centronuclear myopathy, indicates intimate crosstalk among genes involved in the same (or similar) disorders." (PMID 31413155, 2019). "The IMGD dog is the first faithful mammalian model for BIN1-related centronuclear myopathy and particularly for the highly progressive form, and is the only characterized mammalian model available for preclinical trials of potential therapies for this severe congenital myopathy." (PMID 23754947, 2013). "In addition, BIN1 can tubulate membranes separately or in cooperation with dynamin 2 (DNM2), another protein mutated in centronuclear myopathy." (PMID 21797990, 2011). "Centronuclear myopathy (CNM), a severe congenital myopathy characterized by T-tubule defects and muscle weakness, is associated with mutations in three membrane trafficking-related genes: BIN1 (Bridging Integrator-1; also known as Amphiphysin 2, Amph2), DNM2 (Dynamin 2), and MTM1 (Myotubularin 1)." (PMID 41499502, 2026). "Classical centronuclear myopathies in humans have been associated with dominant mutations in the large GTPase DNM2 gene while recessive cases may be due to mutations of amphiphysin 2, encoded by BIN1, and of the ryanodine receptor (RyR1) gene, RYR1." (PMID 25664165, 2015).
centronuclear myopathy (continued). "Its beneficial effect on muscle function was demonstrated in preclinical models of BIN1, DNM2 and MTM1 related centronuclear myopathies." (PMID 38678519, 2024). "Within the group of centronuclear myopathies, MTM1, DNM2 and BIN1 are interconnected due to the role they play in membrane trafficking." (PMID 38678519, 2024). "Preclinical studies showed that the downregulation of DNM2, whose levels are increased also in BIN1 and MTM1-related centronuclear myopathies, resulted in clinical and histological improvements." (PMID 38678519, 2024). "To identify BIN1 mutations affecting its function in skeletal muscle, we sequenced the muscle-specific exon 11 and the adjacent splice-relevant intronic regions in a cohort of 84 patients with various forms of centronuclear myopathy and without mutations in MTM1, DNM2, or in the other BIN1 exons." (PMID 23754947, 2013). "However, we speculate that the mechanism responsible for these observed multinucleated fibers is not the same as in centronuclear myopathies caused by mutations in BIN1, MTM1, or DNM2, as classically those result in the persistence of myofibers with a single, well-centralized nucleus." (PMID 39264856, 2024). "However, SH3 domains are typically promiscuous and it is expected that other, so far unknown partners of BIN1 exist besides DNM2, that also participate in the development of centronuclear myopathy." (PMID 38995680, 2024).
dementia (29 papers, 2013 to 2026). Loss of intellectual abilities interfering with an individual's social and occupational functions. "However, our findings provide a putative pathomechanistic link between the BIN1 rs744373 SNP and the increase in dementia risk as reported by GWAS3." (PMID 30992433, 2019). "Future studies may further test whether BIN1 risk variants are associated with higher rates of increases in pathological tau and faster cognitive decline and conversion to dementia." (PMID 30992433, 2019). "More studies are required to evaluate the role of this and other BIN1 variants in larger populations with different characteristics, to have a greater insight into the relationship between this risk gene and cognitive deficits that might result in dementia." (PMID 39081475, 2022). "Given that APOE ε4 and BIN1 are considered risk factors for AD and that previous studies have shown an association between respiratory diseases such as COPD and dementia, one would expect that carriers of these risk variants would be more prone to RESP." (PMID 39081475, 2022). "BIN1 levels in patients with sporadic AD decreased by 87% compared with those in the non-dementia control group." (PMID 35135506, 2022). "Previous studies have shown that the effect of the APOE gene on the risk of cognitive decline and dementia was modified by other genetic factors, including ABCA7, SORL1, PICALM, CR1, BIN1, and TREM2, showing complex gene-gene interactions." (PMID 34214049, 2021). "There is prior evidence of increased expression of ABCA7, BIN1, and MS4A6A in LOAD brains, and increased ABCA7 expression is associated with clinical dementia rating, with higher expression being associated with more advanced cognitive decline." (PMID 26101835, 2015). "We also used quantitative immunoblotting to measure the level of BIN1 in a series of non-dementia brains covering a wide spectrum of ages." (PMID 24205320, 2013). "Here we measured BIN1 in frontal cortex samples from 24 sporadic AD and 24 age-matched non-dementia brains and correlated the expression of this protein with markers of AD." (PMID 24205320, 2013). "BIN1 declined with age in a cohort of non-dementia control cases between 25 and 88 years but the correlation was not significant (rs=-0.449, p=0.081)." (PMID 24205320, 2013). "Quantitative immunoblotting was used to assess BIN1 level in the frontal cortex in sporadic AD and in age-matched non-dementia controls." (PMID 24205320, 2013). "The interplay between other diseases and dementia needs further clarification, and more studies need to address these associations and how APOE and BIN1 might influence these pathologies." (PMID 39081475, 2022). "Here we find in 89 older individuals without dementia, that BIN1 rs744373 risk-allele carriers show higher AV1451 tau-PET across brain regions corresponding to Braak stages II–VI." (PMID 30992433, 2019). "In this study we measured BIN1 protein level in frontal neocortex from cases of sporadic AD and age-matched control brain samples, the hippocampus of familial AD cases compared to age-matched controls, and in a non-dementia cohort across a range of ages." (PMID 24205320, 2013). "The SNPs rs876461 (PRKD3; P = .02), rs117618017 (APH1B; P = .03), rs4844610 (CR1; P = .04), rs7584040 (BIN1; P = 2 × 10–3), rs11168036 (HBEGF; P = 8 × 10–3), rs143429938 (CLU/MIR6843; P = .04), and rs8064326 (KCTD2; P = 3 × 10‐4) were independently associated with incident dementia." (PMID 33532541, 2021). "This study evaluated the potential utility of BIN1 and TOMM40 genotyping in diagnosing mild cognitive impairment (MCI) and early-stage dementia." (PMID 41465142, 2025). "In a comparative analysis of gene expression in MRI type 2, we found a decrease in the expression of ACOX1, BIN1, CD2AP, CD33, TNFR1, VEGFA, and VEGFC genes in clinically significant CI (MCI and dementia) compared to the control group." (PMID 39125683, 2024).
dementia (continued). "We previously demonstrated that DNMT1 mRNA levels are not regulated in buffy coat samples from patients with AD, whereas DNMT3a expression is downregulated in buffy coats from dementia patients and in the brain of saline-treated APP/BIN1/COPS5 AD mice." (PMID 36432638, 2022). "BDNF expression is decreased in hippocampal and cortical neurons from 21-month APP/BIN1/COPS5 3xTg-AD mice, and is strongly reduced in buffy coat samples from patients with dementia or PD than in healthy control subjects." (PMID 35269588, 2022). "Hence, the current study investigates the association between the BIN1 rs744373 SNP and performance across different cognitive domains, and compares these findings with APOE ε4 allele, the most established risk factor for AD, among healthy ageing men free of severe cognitive impairment or dementia." (PMID 36280690, 2022). "Each cohort had its corresponding age-matched non dementia controls, however, we can not preclude the possibility that the difference between sporadic and familial AD in BIN1 levels is due to the different brain areas investigated." (PMID 24205320, 2013). "The levels of BIN1 protein were reduced in the frontal cortex of sporadic AD compared to age-matched non-dementia controls, but not in the hippocampus of familial AD." (PMID 24205320, 2013). "There are no functional annotations which elucidate how the BIN1 locus might be impacting AD through regulation or modification of TMEM132C, however, TMEM106B is a known dementia-associated gene which has functions in lysosome function and homeostasis." (PMID 38883718, 2024). "BIN1 was reduced by 87% (p=0.007) in sporadic AD compared to non-dementia controls, but BIN1 in sporadic AD did not correlate with soluble Aβ (rs=-0.084, p=0.698), insoluble Aβ (rs=0.237, p=0.269), Aβ plaque load (rs=0.063, p=0.771) or phospho-tau load (rs=-0.160, p=0.489)." (PMID 24205320, 2013).
heart failure (17 papers, 2010 to 2025). Inability of the heart to pump blood at an adequate rate to meet tissue metabolic requirements. "Downregulation of BIN1 has been closely linked to the development and progression of heart failure, including both HFpEF and HFrEF." (PMID 41372804, 2025). "These authors have further proposed that continuous turnover of BIN1 from dyads in healthy patients maintains high levels in blood, explaining why decreased BIN1 plasma levels are linked to heart failure in patients and predict- future arrhythmia." (PMID 30618792, 2018). "Declining BIN1 levels in heart failure are reported to promote not only overall t-tubule loss, but also decreased t-tubule folding." (PMID 30618792, 2018). "Downregulation of BIN1 has been reported in both human and animal models of heart failure, and associated with loss of t-tubules." (PMID 28447290, 2017). "The consequences of BIN1 loss during heart failure are proposed to include macroscale loss of t-tubule membrane and functional dyads, with expected negative consequences for EC coupling efficiency." (PMID 28447290, 2017). "BIN1, its down-regulation was founded to be related to cancer progression and also correlates with ventricular cardiomyopathy and arrhythmia preceding heart failure while increased BIN1 expression maybe linked with increased susceptibility for AD." (PMID 40186323, 2025). "For instance, the bridging integrator 1 (BIN1) is a membrane scaffolding protein that causes CaV1.2 to traffic to T-tubules in healthy hearts and its reduction in heart failure impairs CaV1.2 trafficking." (PMID 39788950, 2025). "In human heart failure, BIN1 expression is reduced, leading to an impairment in Cav1.2 trafficking, calcium transients, and contractility." (PMID 38514804, 2024). "We used a cardiomyocyte-specific PC1-silenced (PC1-KO) mouse model to explore the relevance of cardiomyocyte PC1 in the development of heart failure (HF), considering reduced BIN1 expression induced T-tubule remodeling as a potential mechanism." (PMID 36614108, 2022). "Reduced myocardial BIN1 in heart failure is also detectable at the blood level, and plasma BIN1 predicts heart failure and future arrhythmias in patients with cardiomyopathy." (PMID 36531185, 2022). "The goal of this study was to determine if PIP2-mediated targeting of BIN1 to sarcolemma is compromised during the development of heart failure (HF) and is responsible for TT remodeling." (PMID 35002765, 2021). "BIN1 + 13 + 17 has been suggested to represent a new biomarker of heart failure." (PMID 36614108, 2022). "Indeed, decreased levels of this BIN1 isoform, expressed as an increased score for BIN1 in blood plasma samples from heart failure patients with preserved or reduced ejection fraction, have been reported and related to these pathologies." (PMID 36614108, 2022). "These exciting data suggest that BIN1 may serve as both a biomarker and therapeutic target in heart failure patients." (PMID 30618792, 2018). "While existing data suggest that increasing BIN1 levels in heart failure might simultaneously augment contractility and attenuate arrhythmogenesis, such studies have not yet been conducted." (PMID 28447290, 2017). "It will be interesting in future studies to explore the role of BIN1 regulation in heart failure." (PMID 20169111, 2010). "In this context, the role of BIN1 as important steering wheel for membrane invaginations and consequently for the development of a more mature Ca2+ handling machinery suggests that BIN1 may also represent a promising target for the treatment of heart failure." (PMID 36988697, 2023). "Furthermore, BIN1’s reported role in trafficking LTCCs and RyRs to the dyad may contribute to unpacking of these proteins when BIN1 levels decline during heart failure progression." (PMID 28447290, 2017). "Damaged BIN1 organization was induced in cardiomyocytes with heart failure without reduced protein levels when PIP2 was not present to provide BIN1 membrane insertion." (PMID 40352140, 2025).
breast cancer (15 papers, 2007 to 2025). A primary or metastatic malignant neoplasm involving the breast. "In a mouse model (MMTV/neu) of spontaneous mammary cancer, loss of the tumor suppressor (Bin1) increased IDO expression to support a more aggressive tumor." (PMID 39063133, 2024). "A previous report showed that loss of BIN1 led to nodal metastasis and decreased outcomes for breast cancer patients." (PMID 36475339, 2023). "Our study supports previously obtained data of frequent cancer-associated loss of BIN1 expression in breast cancer." (PMID 17477881, 2007). "For instance, reduced BIN1 expression collaborates with RAS activation to promote tumor progression in breast cancer, highlighting BIN1’s role as a negative regulator of breast cancer carcinogenesis and progression." (PMID 40346580, 2025). "Bin1 has been shown to have tumor suppressor properties and shown to be dysregulated in breast cancer, neuroblastoma, prostate cancer, and melanoma." (PMID 36949070, 2023). "Several studies have indicated Bin1 reduction is a key factor in driving the progression of certain types of tumors, such as childhood neuroblastoma (NB) and breast cancer." (PMID 28152502, 2017). "Complete or partial losses of BIN1 were documented in 60% of breast cancer tissue analyzed by immunohistochemistry or RT-PCR." (PMID 22778941, 2012). "We have identified a 3'-part of BIN1 promoter CpG island among the genomic loci abnormally methylated in breast cancer." (PMID 17477881, 2007). "The BIN1 gene is located on chromosome 2q14 within a region reported to be deleted in 30% to 40% of breast carcinomas." (PMID 17477881, 2007). "BIN1 was found to be downregulated in breast cancer, colon cancer, ovarian cancer, clear cell renal cell carcinoma (RCC), uterine corpus endometrial carcinoma (UCEC), lung cancer, glioblastoma, and liver cancer, suggesting its potential role as a key regulator in cancer progression." (PMID 40346580, 2025). "In contrast, in breast cancer, overexpressed SRSF1, through its function in constitutive and alternative splicing, increases BIN1 isoforms that lack pro-apoptotic functions, thereby causing BIN1 failed interaction with MYC, and leading to MYC-induced epithelial cell transformation." (PMID 38778254, 2024). "In breast cancer, reduced BIN1 expression combined with RAS activation accelerates tumor growth, establishing BIN1 as a key inhibitor of breast cancer development and progression." (PMID 40016843, 2025). "Using hierarchical clustering in the plasma samples cohort, we found significant promoter hypermethylation of eight genes (APC, BIN1, BRCA1, CST6, GSTP1, P16, P21 and TIMP3) in patients' plasma of breast cancer patients compared with plasma of normal subjects." (PMID 21283676, 2011). "BIN1 is a well-studied tumor suppressor that expressed at low levels or even lost in numerous cancers, including NSCLC, ESCC, oral squamous cell carcinoma (OSCC), melanoma, and breast cancer." (PMID 35149697, 2022). "To achieve a gene panel for developing a breast cancer blood-based test we quantitatively assessed the DNA methylation proportion of 248 CpG sites per sample (total of 31,248 sites in all analyzed samples) on 10 candidate genes (APC, BIN1, BMP6, BRCA1, CST6, ESR-b, GSTP1, P16, P21 and TIMP3)." (PMID 21283676, 2011). "Notwithstanding the findings of genetic alterations, including allelic deletions, of BIN1 in breast cancer (BC), their frequencies are not sufficient to be responsible for all the cases of BIN1 losses occurring at the level of protein and/or message, suggesting a role for epigenetic factors." (PMID 17477881, 2007).